INS (insulin)
Diseases named in the same sentence as INS in open-access papers (continued):
Sharing a sentence is not in itself a finding about the gene and the disease.
diabetes (continued). "This requires a high level of education of the person with diabetes in managing their condition, access to insulin, oral medications, and monitoring equipment." (PMID 32456637, 2020). "Adiponectin is a cardioprotective adipokine that dampens endogenous hepatic glucose production, improves insulin sensitivity, negatively correlates with body mass, and is often decreased in the presence of insulin resistance and/or diabetes mellitus." (PMID 33081175, 2020). "We believe that postoperative diabetes can be well controlled with oral hypoglycemic drugs and insulin." (PMID 32219139, 2020). "This study, however, found a markedly higher risk for ADHD for offspring of severely obese mothers with insulin-treated PGDM (HR = 6.03, 95% CI = 3.23–11.24; HRno diabetes, severe obesity=1.88, 95% CI = 1.58–2.23)." (PMID 32494038, 2020). "Alloxan furthermore selectively prevents glucose-mediated secretion of insulin via its capacity to prevent the β-cell glucose sensor glucokinase in streptozotocin-induced diabetes." (PMID 33317171, 2020). "The most common forms of diabetes have been defined by clinical differences in insulin dependence to maintain glucose homeostasis, the age and abruptness of onset of symptoms, and tendency for ketosis." (PMID 32797243, 2020). "Disturbance of insulin signaling eventually leads to glucose intolerance, diabetes, dyslipidemia, and coronary artery disease." (PMID 32610588, 2020). "In the case of diabetes, inadequate insulin protects the physiology from receiving glucose from the blood into the body’s cells for supply energy." (PMID 32365537, 2020). "Excess mortality was substantially higher in people who were diagnosed with T2DM at a younger age, died at a younger age, who had a longer diabetes duration, and those who required treatment with insulin." (PMID 32962295, 2020). "Diabetes management involves a regimen of daily blood glucose monitoring, insulin administration, and carbohydrate monitoring, a complex and demanding care routine that is primarily under the control of the patient." (PMID 33079068, 2020). "The nano-SAC can improve diabetes-induced reproductive dysfunction by regulating glucose, insulin, and oxidative enzyme and by increasing the level of testosterone, follicle-stimulating hormone, luteinizing hormone, and sperm count as well as sperm mobility." (PMID 32606672, 2020). "The proposed benefits of physical activity have been well documented, including reduced levels of inflammation, improved insulin sensitivity (including in diabetics), lipid metabolism and protection against the destruction of pancreatic ß-cells." (PMID 32085709, 2020). "NPY levels are significantly greater in women, patients with diabetes (especially insulin controlled), and patients with hypertension (especially those taking hydralazine)." (PMID 31876927, 2020). "Compared with the NCVN group, the age, course of diabetes, use of insulin, use of metformin, FBG, HbA1c, BUN, SDBG, LAGE, MBG, MDA, and TXNIP values significantly higher in the NCVA group (P < 0.05)." (PMID 32774321, 2020). "Since East Asians, including Japanese, develop diabetes with relatively low adiposity and insulin resistance as compared to those in Caucasians, it is suggested that impaired insulin secretion is more involved in the onset of diabetes in this population." (PMID 32630741, 2020). "In this context, the effect of Iranian propolis on glucose metabolism, insulin resistance, and renal and liver function, in addition to inflammatory biomarkers in patients with type 2 diabetes mellitus, was evaluated." (PMID 33383693, 2020). "Higher than normal fasting blood glucose with normal serum insulin levels among the diabetic CHC population of this study favors pathogenesis of HCV induced diabetes mellitus by some other etiological factor." (PMID 33520544, 2020).
diabetes (continued). "For instance, pay attention to patients with diabetes who are struggling with insulin therapy, obesity and suffer from diabetic complications, low self-efficacy and social support, which all associate with suboptimal HRQoL36–38." (PMID 32433470, 2020). "Most patients with obesity, T2DM and CKD in our cohort were treated with diabetes therapy which promotes weight gain: insulin and sulphonylureas." (PMID 32845571, 2020). "BCAA: the first report of BCAA (i.e., valine, isoleucine, and leucine) correlation with insulin resistance, impaired insulin signaling and diabetes appeared in 1970." (PMID 32708684, 2020). "A decrease in ceramide concentrations in insulin-sensitive tissues was observed in dexamethasone-induced diabetes treated mice compared to ceramide concentrations observed in control mice." (PMID 32849282, 2020). "Generation of insulin-producing cells from human pluripotent stem cells (hPSCs) in vitro would be useful for drug discovery and cell therapy in diabetes." (PMID 33198821, 2020). "The prevalence of food insecurity (FI) and insulin rationing among patients with diabetes who present to the emergency department (ED) is unclear." (PMID 32726270, 2020). "Nevertheless, the UK Prospective Diabetes Study (UKPDS) compared intensive diabetes treatment using SUs or insulin with conventional (diet) control; the study demonstrated that the use of SUs does not carry a high risk of CV disease." (PMID 33315940, 2020). "The moderate inhibitory effect of 2g and 2h against β-secretase, on the other hand, would enhance insulin signalling during diabetes." (PMID 32156083, 2020). "PIR relates exclusively to insulin while diabetes self‐care encompasses overall diabetes management, including diet, exercise and glycaemic control." (PMID 32257276, 2020). "More specific instruments have the advantage of better assessing the unique aspects of a particular disease as well as its impact on patients’ lives, such as questions asking patients with diabetes about the burden of using insulin in public." (PMID 32236314, 2020). "Stressed and inflamed beta cells are functionally compromised and cannot adapt to effectively respond to increased insulin demand which advances beta cell dysfunction towards failure and diabetes." (PMID 33182622, 2020). "There are currently 3 types of medical management products on the market for patients with diabetes: blood glucose level monitoring equipment, injectable insulin, and implantable insulin pumps." (PMID 33164904, 2020). "In both countries, the average diabetes duration was about 7 years and the average insulin dose was 0.9 ± 0.3 units per kg body weight." (PMID 32704558, 2020). "We found that patients with diabetes control blood glucose levels with insulin or oral medicine before admission." (PMID 32233013, 2020). "Despite mounting evidence that defects in beta cell function do not fully account for the dysregulation observed in diabetes, current therapies for diabetes (both type 1 and type 2) have focused almost exclusively on the insulin-producing beta cell." (PMID 32382023, 2020). "Diabetes can exacerbate chronic inflammation, formation of advanced glycation end-products and aberrant insulin signalling, which trigger tumour formation and progression." (PMID 31980687, 2020). "In our previous study, 28% of patients with T2D reported they discontinued non-insulin diabetes medication use due to financial reasons and 8% had initiated insulin use due to the same reasons within the first 11 months after the implementation of the new SRS." (PMID 33246453, 2020). "Type 2 diabetes mellitus is resultant of structural and functional changes in the beta cells of pancreas and is characterized by the reduced insulin secretion." (PMID 32148658, 2020). "Restoration of SphK2 expression and pharmacological depletion of sphingosine levels substantially improved hepatic insulin sensitivity, which provides a potential therapeutic option against diabetes." (PMID 32917816, 2020).
diabetes (continued). "A typical model, used in pharmacology, is to damage pancreatic β-cells through STZ to realize insufficient insulin secretion, thus inducing hyperglycemia and diabetes." (PMID 33643038, 2020). "According to the present study, the odds of depression is increased by 24.46 times among diabetes patients who are taking both oral antidiabetic medication and insulin than those who are taking only oral antidiabetic medication." (PMID 33145110, 2020). "We recommend that health care professionals should work on providing health education to the patients during follow up and providing community service on the knowledge of diabetes, self-care practice and administration of insulin." (PMID 32528672, 2020). "Insulin-dependent diabetes mellitus (IDDM) is a disorder initiated by progressive damage to insulin-secreting β cells." (PMID 32133389, 2020). "Approximately 8 million people with diabetes are prescribed insulin in the United States, highlighting the importance of the devices that deliver insulin." (PMID 31833010, 2020). "Insulin, home blood glucose monitoring, antenatal testing, and oral hypoglycemic agents have revolutionized the management of diabetes during pregnancy, leading to drastic reductions in maternal and infant mortality attributable to diabetic complications." (PMID 33408574, 2020). "The selected articles showed that turmeric had some beneficial effect on diabetes, such as better blood glucose and insulin sensitivity control, also acting as a protective factor of cells against inflammatory mediators." (PMID 33396291, 2020). "When adjusted for other baseline demographic factors, procedure, gender, and duration of diabetes were all independent predictors of cessation of insulin use after surgery (p < 0.001)." (PMID 33285553, 2020). "In Diabetes, platelet dysfunction occurs due to intracellular hyperglycemia related to insulin-independent glucose transporters in the platelet cell membrane." (PMID 33031385, 2020). "At present, there are many drugs available for diabetes treatment, but most of the mechanisms of drug action cannot be separated from the role of insulin." (PMID 32656265, 2020). "Since then, insulin has saved millions of lives and fundamentally altered the course and prognosis of diabetes." (PMID 32002701, 2020). "Among diabetes- and obesity-related factors, insulin and insulin-like growth factor 1 down-regulated 11β-HSD1 expression in fibroblasts and myeloid cells, while glucose, fatty acids, TNF-α and IL-1β did not affect it." (PMID 33260645, 2020). "Intraperitoneal administration of STZ (45-55 mg/kg body weight) decreased insulin sensitivity and induced hyperglycemia and diabetes mellitus in mice and rats." (PMID 32104545, 2020). "In this study, we demonstrated an association between hypoglycemic episodes, norepinephrine release and uncontrolled arterial hypertension in diabetes patients on insulin therapy." (PMID 33292431, 2020). "The 100th anniversary of the discovery and commercial availability of insulin as a treatment for diabetes is approaching." (PMID 32396624, 2020). "There are several different types of diabetes, the most common form in the general population being type 2 diabetes (non-insulin-dependent), mostly affecting adults and accounting for about 90% of all cases of diabetes." (PMID 32708865, 2020). "Since the beginning of the 21st century, multiple studies have highlighted the potential links between AD and abnormalities of insulin signaling related with diabetes." (PMID 32503113, 2020). "By acting as a powerful miR-7 inhibitor, CDR1as promotes islet β-cells proliferation and insulin secretion in diabetes through sponging miR-7 and enhancing Myrip and Pax6 gene expression." (PMID 32182790, 2020). "Diabetes mellitus (DM) is a chronic metabolic disease characterized by hyperglycemia resulting from a defect in insulin secretion, insulin sensitivity, or both." (PMID 32751658, 2020).
diabetes (continued). "When β-cells are damaged by various factors, absolute (D1M) or relative (D2M) insufficient insulin secretion follows, ultimately resulting in hyperglycaemia and diabetes." (PMID 32659127, 2020). "In the second study, participants received oral insulin capsules daily (7.5 mg/day) and were followed up for a mean duration period of 4.3 years; the primary endpoint was the diagnosis of diabetes." (PMID 32204344, 2020). "Systemic inflammation influences insulin signaling and sensitivity, and downregulates adipokine production, which ultimately leads to insulin resistance and diabetes." (PMID 31973745, 2020). "Decrease of the first phase and low second phase insulin release is characteristic of type 2 diabetes mellitus (T2DM)." (PMID 32831835, 2020). "In humans, the significance of KCNJ11 in insulin secretion was suggested by its function in permanent neonatal diabetes and familial persistent hyperinsulinemic hypoglycaemia of infancy." (PMID 33101408, 2020). "In line with these experimental findings, several cross-sectional and prospective epidemiologic studies have associated low IGFBP-1 levels with obesity, high fasting insulin, impaired glucose tolerance, and diabetes in middle-aged individuals." (PMID 32492897, 2020). "This is a huge step for the AI application in the automomic calculation of insulin dosage and would tremendously improve the metabolic control of insulin-treated patients with diabetes." (PMID 32548087, 2020). "Of the 190 (65.7%) patients with diabetes treated with metformin, 82 (28.37%) were on other oral agents and/or insulin." (PMID 32385343, 2020). "Direct transdifferentiation of adult somatic cells into insulin-producing cells (IPCs) is a promising approach for cell-based therapies for type 1 diabetes mellitus." (PMID 32655618, 2020). "Of the 83 patients, 27 (32.9%) used to receive oral medicine and 55 (67.1%) used insulin for the control of diabetes." (PMID 32566310, 2020). "The availability of oral insulin would free millions of people with diabetes from the everyday burden of subcutaneous (SC) insulin injections." (PMID 32719315, 2020). "Diabetes is characterized by increased blood glucose levels due to the dysfunctional sensing or production of insulin." (PMID 32560282, 2020). "Diabetes mellitus, with a reduction in insulin sensitivity or insulin release, is a comorbidity of both AD and PD, with an increased risk of developing these neurodegenerative disorders in patient with diabetes." (PMID 33100956, 2020). "In this review, we discuss the current research advances in strategies to obtain insulin-producing cells (IPCs) from different precursor cells and in stem cell-based therapies for diabetes." (PMID 32641151, 2020). "These MSC-derived EVs also showed a distinctive miRNAs cargo, being enriched in miRNA-targeting genes involved in the development of metabolic disease and its complications, including diabetes, obesity, and insulin signaling." (PMID 32858940, 2020). "The software integrates outcomes for diabetes management (previous blood glucose levels, insulin doses, and carbohydrates consumed) and challenges participants to predict their next glucose level based on a graphical display." (PMID 33066372, 2020). "Exact mechanisms remain hypothetical at this point, especially considering the heterogeneity in insulin secretion of pre-diabetes and type 2 diabetes mellitus, ranging from hyperinsulinemia to varying degrees of beta-cell dysfunction." (PMID 32708966, 2020). "The probable causes of T2D are described, and the strengths and weaknesses of insulin administration, the most prevalent therapy for diabetes, are evaluated." (PMID 33167495, 2020). "We analyzed the long-term effect of these insulin fused to apolipoprotein A-I or insulin fused to albumin using AAVs in the db/db mouse model of diabetes, obesity, and liver steatosis." (PMID 33679386, 2020).
diabetes (continued). "All patients with diabetes mellitus were receiving oral therapy (metformin/sulfonylureas/gliptins), and one patient was also receiving insulin." (PMID 32401607, 2020). "Together, our results support that neutralising HMGB1 reversed new-onset diabetes, decreased insulitis and preserved insulin-staining islets in diabetic NOD mice." (PMID 32072192, 2020). "Baseline diabetes was defined as a fasting glucose concentration of 126 mg dl−1 or higher, or the reported use of hypoglycaemic medication or insulin treatment." (PMID 34321718, 2020). "Diabetes mellitus (DM), one of the most common diseases in the world, results from impairments in insulin secretion and/or insulin action leading to disturbances in the metabolism of carbohydrates, lipids, and proteins." (PMID 32655759, 2020). "We describe a 67 year-old Japanese man who manifested severe hypouricemia (0.7 mg/dl (3.8–7.0 mg/dl), 41.6 μmol/l (226–416 μmol/l)) and diabetes with impaired insulin secretion." (PMID 32375679, 2020). "Of note, supplementation of magnesium is easy, low-cost and was shown to improve insulin sensitivity, glucose metabolism and to retard progression from pre-diabetes to overt diabetes." (PMID 31650393, 2020). "Among the patients with diabetes (18,207/92,751) insulin was given to 942 patients, but only 824 of these had a documented intraoperative blood glucose." (PMID 32381036, 2020). "None of the prescriptions was found in Step 3 combinational therapy for diabetes; however, fourth step-based results were 36%, mostly insulin." (PMID 32551141, 2020). "Protein–tyrosine phosphatases (PTP) including PTP1B and Low molecular weight PTP (LMPTP), are negative regulators of the insulin signaling pathway and are considered a promising therapeutic target in the treatment of diabetes." (PMID 32369900, 2020). "A number of different classes of agents can modulate TXNIP expression, including PPAR-γ agonists, which include classes of drugs with insulin-sensitizing properties used for treating diabetes." (PMID 33302545, 2020). "This score used one demographical variable (age), three variables of medical history (type of diabetes, insulin treatment, hypertension) and one clinical variable (peripheral oxygen saturation on room air at admission)." (PMID 33233575, 2020). "We found EN-RAGE as a novel inflammatory marker for pre-diabetes and for CHD, IL17 for incident T2D and IL13 for pre-diabetes, incident T2D and insulin therapy." (PMID 32367290, 2020). "All people with T1DM were treated with insulin, with 1.6% receiving metformin and surprisingly 9.8% were recorded as being prescribed sulphonylureas in addition to their insulin which casts doubt on the accuracy of the designated type of diabetes recorded." (PMID 32385543, 2020). "Researchers believe that rs1801282 causes increased sensitivity to insulin, total cholesterol, HDL (high-density lipoprotein) and increased glucose utilization, which serves as a protective mechanism against diabetes mellitus and obesity." (PMID 32230794, 2020). "We wanted to investigate possible associations of polymorphisms in genes involved in vitamin D metabolism with indices of insulin resistance and insulin secretion, and also with development of diabetes after gestational diabetes mellitus (GDM)." (PMID 32407388, 2020). "Rs738409 in PNPLA3 gene has been confirmed to have effect on diabetes, insulin, insulin resistance and body mass index too." (PMID 32961860, 2020). "According to the American Diabetes Association (ADA), diabetes care is mainly based on insulin delivery." (PMID 32484447, 2020). "Especially, Glucose-responsive system plays an important role in self-regulated insulin delivery to treat diabetes." (PMID 33614595, 2020). "The basis of the abnormalities in the metabolism of carbohydrate, fat, and protein in diabetes is insufficient action of insulin on target tissues." (PMID 33424989, 2020).